BDNF (brain derived neurotrophic factor)
Diseases named in the same sentence as BDNF in open-access papers (continued):
Sharing a sentence is not in itself a finding about the gene and the disease.
allergic asthma (5 papers, 2012 to 2025). A asthma with a basis in a pathological type I hypersensitivity reaction. "This is further substantiated by the fact that allergen provocation also induces varying BDNF levels in AR and allergic asthma." (PMID 37047077, 2023). "In patients with allergic asthma, a close relationship between elevated systemic BDNF concentrations and lung function has been demonstrated, whereas systemic TGF-β1 concentrations were normal." (PMID 23245944, 2012). "Increased production of BDNF from immune cells, including infiltrating T-cells and macrophages, contributes to the development of inflammation during allergic asthma, promoting neuronal changes leading to airway smooth muscle contraction and mucus hypersecretion." (PMID 40380033, 2025). "Furthermore, elevated concentrations of BDNF in platelets correlate with bronchial hyperresponsiveness in allergic asthma, and inhibition of BDNF reduces neuronal hyperreactivity to allergens, as shown in an animal model." (PMID 37047077, 2023). "In addition, the frequencies of BDNF Val66Met genotypes (p = 0.27), alleles (p = 0.18), GG vs. A allele carriers (p = 0.24), and AA vs. G carriers (p = 0.55) were not significantly different between non-allergic and allergic asthma patients." (PMID 33114368, 2020). "However, our results did not mirror earlier studies showing that patients with allergic asthma have higher BDNF levels compared to control subjects." (PMID 33114368, 2020).
amblyopia (5 papers, 2019 to 2025). Decreased vision that results from abnormal visual development. "While the present findings in mice on the superiority of BV over RO may have little direct relevance to the treatment of human amblyopia, the fact that BDNF production precedes and appears to be causal for the strengthening of a cortical pathway may indeed have great import for therapy." (PMID 36634145, 2023). "The increased expression of BDNF correlates with improved visual acuity in animal models of amblyopia." (PMID 36816499, 2023). "In this study, we measured BDNF polymorphisms because they have been linked to neuroplasticity and an increase in BDNF expression has been identified as a key mechanism in SSRI-induced recovery from amblyopia in mature rats." (PMID 31281343, 2019). "It is therefore feasible that for those individuals who find the amblyopia treatment process distressing, may also face raised cortisol levels and decreased BDNF levels which in turn might hamper their responsiveness to amblyopia treatment by reducing neuroplasticity." (PMID 39831149, 2025).
autonomic dysfunction (5 papers, 2018 to 2025). "Both conditions have been associated with autonomic dysfunction, neuroinflammation, and dysregulation of neurotrophic factors such as brain-derived neurotrophic factor (BDNF), leading to retinal ganglion cell (RGC) degeneration." (PMID 41271998, 2025). "Taking into account telemetric data, all defeated animals were vulnerable to autonomic dysfunction, but only animals with persistent lower BDNF levels (Dlow) were vulnerable to long-lasting cardiovascular alteration." (PMID 33344701, 2020). "In SCI, autonomic dysfunction and reduced systemic vascular shear stress during acute exercise may impair the BDNF response." (PMID 36451805, 2022). "Reduced serum levels of BDNF correlated with age, adrenergic and sudomotor function, overall autonomic dysfunction, and the autoregulation index calculated in Phase II of the Valsalva maneuver, and showed associations with focal to bilateral tonic-clonic seizures." (PMID 30524358, 2018). "In addition, we believe that BDNF, being a neurotrophic factor, may reflect the autonomic dysfunction presented by patients with ChC." (PMID 30133549, 2018).
bacterial meningitis (5 papers, 2014 to 2022). Inflammation of the membranes surrounding the brain and spinal cord due to a bacterial infection. "There is increasing evidence from animal experiments and clinical studies indicating that BDNF exerts neuroprotective effects on bacterial meningitis." (PMID 32676082, 2020). "Better understanding of how BDNF is regulated can be helpful to find a therapeutic target in bacterial meningitis." (PMID 28615695, 2017). "Similarly, the serum and cerebrospinal fluid (CSF) BDNF levels were also increased in pediatric patients with bacterial meningitis." (PMID 32676082, 2020). "Our results indicated that treatment with exogenous BDNF might constitute a potential therapeutic strategy for the treatment of bacterial meningitis." (PMID 28778220, 2017). "During bacterial meningitis, elevated levels of BDNF in serum and CSF have been reported." (PMID 25409333, 2014). "Moreover, administration of exogenous BDNF for 7–28 days might increase the proliferation and differentiation of NSCs in the hippocampus after bacterial meningitis." (PMID 32676082, 2020). "Here, exogenous BDNF administration increased IL-10 expression at the transcription and translation levels, suppressed proinflammatory cytokine expression, and enhanced anti-inflammatory cytokine expression in bacterial meningitis models, which was consistent with observations from previous studies." (PMID 28778220, 2017).
brain cancer (5 papers, 2017 to 2025). A primary or metastatic malignant neoplasm affecting the brain. "The role of BDNF and its cognate receptor TrkB in cancer, including brain cancer, has been recognized for a long time." (PMID 33096634, 2020).
brain inflammation (5 papers, 2018 to 2023). "Brain inflammation causes the suppression of BDNF and caludin-5 expression." (PMID 31413350, 2019).
cocaine abuse (5 papers, 2015 to 2023). Disorders related or resulting from use of cocaine. "In other D1R-rich brain regions, such as PFC and hippocampus, cocaine abuse could alter p-ERK 40, p-CREB 41 and BDNF 42,43." (PMID 37351159, 2023). "The present study has shown that long-term behavioral sensitization to cocaine is accompanied by increases in BDNF, TrkB, p75NTR, ILK, and phospho-Ser473 Akt protein levels in the mPFC and NAc core — two brain areas that have been demonstrated to be intimately involved in cocaine abuse." (PMID 26538265, 2015).
Constipation (5 papers, 2016 to 2025). Infrequent or difficult evacuation of feces. "Significant decreases in the expression of both NT-3 and BDNF were observed in the tissues of constipation model mice relative to the normal group." (PMID 32974216, 2020). "Furthermore, BDNF expression in mucosal epithelial and lamina propria cells was reported to be lower in slow-transit constipation patients." (PMID 27134753, 2016). "ICR mice and SR rats with loperamide (Lop)-induced constipation exhibited a decrease in the level of two ICC markers (C-kit and SCF) and the other enteric nerve-related factors (PGP9.5, brain-derived neurotrophic factor (BDNF), and GNDT)." (PMID 35743302, 2022).
disc degeneration (5 papers, 2014 to 2025). "Lastly, neurotrophic factors include NGF and brain-derived neurotrophic factor (BDNF), which are upregulated during disc degeneration and promote nerve ingrowth and pain." (PMID 41304859, 2025).
Friedreich ataxia (5 papers, 2020 to 2024). An inherited condition that affects the nervous system and causes movement problems. "Another prevalent type of ataxia, where the therapeutic potential of BDNF has been investigated, is Friedreich’s ataxia (FRDA), which is a hNDD caused by mutations in the FXN gene, causing motor dysfunction, as well as cardiopathies." (PMID 39200370, 2024).
heroin addiction (5 papers, 2017 to 2025). "The pathophysiology of heroin addiction and withdrawal syndrome has been linked to BDNF, as previous studies found that heroin users have lower serum BDNF levels despite having higher serum BDNF levels during early abstinence." (PMID 38334898, 2024). "However, the BDNF 'Val68Met' polymorphism was found to increase compulsive alcohol drinking in mice, and the BDNF rs6265, rs11030104, and rs10767664 were reported to be associated with decreased heroin addiction risk." (PMID 38334898, 2024). "Additional systems biology results indicated heroin dependence as the highest-risk manifestation linked to these genes, and PGx analyses suggested DRD1, DRD2, BDNF, and OPRM1 as promising targets for future studies." (PMID 41333412, 2025). "They noted, however, that AA BDNF rs6265 carriers had an earlier onset of heroin addiction and a more pronounced trend in a family history of heroin addiction than GG carriers after controlling for behavioural characteristics within rs6265 genotypes." (PMID 38255861, 2024).
hypersomnia (5 papers, 2015 to 2025). A sleep disorder characterized by excessive sleepiness. "Our results also implicate BDNF in improvements in sleep quality following exercise, as decreases in BDNF were associated with decreased hypersomnia." (PMID 26241349, 2015). "In this scenario, decreased BDNF production would be associated with decreases in hypersomnia, which matches our findings." (PMID 26241349, 2015). "After a 12-week aerobic exercise intervention, participants exhibited reductions in brain-derived neurotrophic factor, interleukin-1β, and hypersomnia." (PMID 28458924, 2017). "In summary, there was a significant correlation between change in IL-1β and change in hypersomnia (ρ=−0.37, P=0.003) and between change in BDNF and change in hypersomnia (ρ=0.26, P=0.029)." (PMID 26241349, 2015). "Reduction in hypersomnia was correlated with reductions in BDNF (ρ=0.26, P=0.029) and IL-1β (ρ=0.37, P=0.002)." (PMID 26241349, 2015). "The fact that changes in IL-1β and BDNF were only related to changes in hypersomnia further support the need to identify biological markers that differentiate across different symptom profiles." (PMID 26241349, 2015). "Specifically, reductions in BDNF and IL-1β are related to reductions in hypersomnia." (PMID 26241349, 2015). "In conclusion, improvement in hypersomnia is related to reductions in inflammatory markers and BDNF in persons with non-remitted MDD." (PMID 26241349, 2015).
melancholic depression (5 papers, 2013 to 2025). "Serum BDNF levels in the people with MD with melancholia (8.6 ± 2.2 ng/mL) were significantly lower than in the people with MD with non-melancholia (10.3 ± 3.1 ng/mL)." (PMID 29541037, 2018).
metastatic disease (5 papers, 2013 to 2024). "The in vivo data indicates that perioperative hyperoxia enhances metastatic disease and this effect could be BDNF mediated." (PMID 32183322, 2020).
Neurodegeneration (5 papers, 2011 to 2025). Progressive loss of neural cells and tissue. "Neurotrophins, including nerve growth factor (NGF) and brain-derived neurotrophic factor (BDNF), were studied to assess the possibility of preventing retinal neurodegeneration in DR and, consequently, to avert retinal vascular damage." (PMID 40564047, 2025). "Investigations examining the effect of exercise on changes in circulating BDNF concentrations have gained much interest as a possible target for the therapy and/or prevention of stress and neurodegeneration-related disorders 22,34,35." (PMID 33173426, 2020). "Owing to its various roles in modulating synaptic functions, a BDNF-based synaptic repair strategy has been proposed to treat neuro-degenerative diseases." (PMID 31165005, 2019).
Optic neuropathy (5 papers, 2014 to 2022). "Similar to BDNF, the cytokine has been shown to attenuate RGC loss in animal models of various optic neuropathies." (PMID 34827174, 2021). "In a genetic model of optic neuropathy, increased BDNF was seen in the vesicles of hypertrophic astrocytes, whereas BDNF mRNA was somewhat downregulated." (PMID 31105589, 2019). "Previous studies have demonstrated that BDNF increases RGCs survival in experimental models of optic neuropathies." (PMID 28101532, 2017). "Experimental studies in various disease models addressed mechanisms of action and indicated modulation of neurotrophic factors (IGF-1, BDNF, CNTF, FGF-2, TNF-α) and immunomodulators (IL-10, IL-6, COX-2, NF-κB) by electrical stimulation of the eye in optic neuropathies." (PMID 35361287, 2022).
preeclampsia (5 papers, 2015 to 2024). Preeclampsia is a hypertensive disorder of pregnancy that is characterized by new-onset hypertension with proteinuria presenting after 20 weeks of gestation, and depending on mild or severe forms may initially present with severe headache, visual disturbances, and hyperreflexia. "They found a decline in the concentration of BDNF with the duration of pregnancy in both groups, and a significantly lower concentration of BDNF was found in pregnant women with preeclampsia compared to healthy controls." (PMID 36771307, 2023). "In preeclampsia, placental and cord blood BDNF levels are also increased, with possible consequences for fetal neurodevelopment." (PMID 26501045, 2015). "Decreased BDNF levels during pregnancy are due to abnormal placental development in preeclampsia; the authors conclude that it might involve placental development." (PMID 36771307, 2023). "Altered head growth in preeclampsia may be explained by increased fetal exposure to neurotrophins, including BDNF." (PMID 26501045, 2015). "Accordingly, increased fetal exposure to BDNF at term may explain increased head growth in preeclampsia, although further studies are needed." (PMID 26501045, 2015). "In term preeclampsia, elevated BDNF is also observed in both the placenta and the cord blood." (PMID 26501045, 2015). "In all, sixty (n = 60) pairs were excluded: twelve (n = 12) pairs due to twin pregnancies, n = 12 due to fetal anomalies, n = 9 due to preeclampsia, and n = 26 due to maternal diseases that could affect maternal BDNF (psychiatric disorders n = 19, neurological disorders n = 7)." (PMID 35736415, 2022). "Other studies have also shown a decrease in BDNF during pregnancy in healthy and pathological conditions, in maternal depression in pregnancy, in pregnant women with T1DM, and preeclampsia." (PMID 36771307, 2023).
primary Sjögren’s syndrome (5 papers, 2010 to 2025). "Furthermore, recent clinical findings highlight tear BDNF as a predictor of mental health and sleep quality in patients with Sjögren’s syndrome-associated DED, emphasising the complex interplay between ocular and neuropsychiatric pathways." (PMID 41226736, 2025). "Elevated circulating BDNF levels have been reported in patients with Sjögren’s syndrome, possibly reflecting a compensatory response to chronic ocular inflammation." (PMID 41226736, 2025). "The effect of increased serum levels of BDNF in patients with systemic autoimmune diseases, such as RA or primary Sjögren’s syndrome, worth further investigation." (PMID 33673283, 2021). "Increased BDNF levels in sera have also been reported in primary Sjögren’s syndrome, which correlates with systemic activity and B and T cell activation." (PMID 24223945, 2013). "In contrast, BDNF serum levels are enhanced in primary Sjögren syndrome patients (pSS) treated with either corticosteroid or immunosuppressants for severe systemic involvement." (PMID 24223945, 2013). "Increased NGF and BDNF plasmatic levels have also been recently reported in primary Sjögren's syndrome in correlation with systemic activity and B and T cell activation." (PMID 21085492, 2010).
proliferative diabetic retinopathy (5 papers, 2013 to 2024). Advanced retinopathy due to diabetes mellitus characterized by the formation of new vessels in the retina. "Patients suffering from proliferative diabetic retinopathy had a decreased level of BDNF in the serum compared to a healthy control group and diabetic patients with no retinopathy." (PMID 32012942, 2020). "We investigated the expression of the NTs nerve growth factor (NGF), brain-derived neurotrophic factor (BDNF), neurotrophin-3 (NT-3), and neurotrophin-4 (NT-4) and their receptors TrkA, TrkB, and TrkC in proliferative diabetic retinopathy (PDR)." (PMID 23762379, 2013). "The mean serum levels of BDNF in the control group, diabetic patients without retinopathy, and proliferative diabetic retinopathy (PDR) patients were 25.5 ± 8.5, 21.8 ± 4.9, and 10.01 ± 8.1 ng/ml, respectively." (PMID 39712817, 2024). "They revealed that BDNF levels were lower in patients suffering from proliferative diabetic retinopathy and non-proliferative diabetic retinopathy compared to the control group." (PMID 32012942, 2020).
retinal ischemia (5 papers, 2012 to 2023). A ischemic disease that involves the retina. "In animal models of retinal ischemia-reperfusion, early injection of BDNF into the vitreous cavity can reduce the apoptosis of retinal nerve cells." (PMID 34975295, 2022). "In the retinal ischemia-reperfusion model, BDNF plays a very important role in the functional recovery of experience-dependent retinal cells." (PMID 34975295, 2022). "Its activation can protect RGCs against death in a rat model of retinal ischemia-reperfusion via the brain-derived neurotrophic factor (BDNF) pathway." (PMID 35185615, 2022).
retinoblastoma (5 papers, 2016 to 2023). A malignant tumor that originates in the nuclear layer of the retina. "MiR-382 inhibited cell proliferation and invasion of retinoblastoma by targeting BDNF-mediated PI3K/AKT signaling pathway." (PMID 33013313, 2020). "Gao Y showed that BDNF could induce a higher expression of HIF-1α via the activation of TrkB in human Y-79 retinoblastoma cells, which consequently contributed to its effect against chemotherapeutic agent-induced cytotoxicity and apoptosis." (PMID 27852063, 2016).
synucleinopathy (5 papers, 2016 to 2022). A neurodegenerative disease that is characterized by the abnormal accumulation of aggregates of alpha-synuclein protein in neurons, nerve fibers or glial cells. "In particular, the impact of STN DBS on α-synuclein (α-syn) aggregation, inclusion-associated neuroinflammation, and BDNF levels has yet to be examined in the context of synucleinopathy." (PMID 33472823, 2021). "In another genetic PD model induced by ganglioside GM2 synthase mutation, FTY720 reduced brachial plexus synucleinopathy, increased BDNF level, and improved PD-associated age-onset motor symptoms and bladder function." (PMID 34207975, 2021). "What remains unknown is the potential for BDNF to mitigate inclusion-associated dysfunction within the context of synucleinopathy." (PMID 33846345, 2021). "Can BDNF counteract synucleinopathy-associated pathogenesis?" (PMID 33846345, 2021). "Curiously, HMW aSyn in ANA-12-treated Tg colon was markedly increased 14-fold above vehicle after a 3-month Trk-B blockade, suggesting that loss of BDNF signaling in the gut may accelerate ENS synucleinopathy." (PMID 27528608, 2016). "The present data indicate that the α-synucleinopathy in the raphe 5-HT neurons evoked a widespread alteration of 5-HT function and of BDNF expression in HPC." (PMID 35210396, 2022). "Beyond synucleinopathy, impaired BDNF signaling has been documented in other neurodegenerative disorders, including Alzheimer’s disease." (PMID 33846345, 2021). "What remains unknown is whether therapeutic strategies that increase BDNF or TrkB signaling can exert neuroprotective effects within the context of synucleinopathy." (PMID 33846345, 2021). "It is therefore possible that increased BDNF expression could counteract the pathological consequences of synucleinopathy." (PMID 33846345, 2021). "All FTY720s were reported to increase BDNF expression and stimulate the catalytic activity of protein phosphatase 2A (PP2A), function of which is disturbed in synucleinopathy." (PMID 34207975, 2021). "Lastly, we evaluate the ability of STN DBS to drive BDNF production in the striatum and M1 cortex in the context of PFF-seeded synucleinopathy." (PMID 33472823, 2021). "Cumulatively, the data lead us to propose a model in which FTY720 stimulates BDNF expression, which improves gut motility and reduces gut synucleinopathy in the ENS of young and old synucleinopathy mice." (PMID 27528608, 2016).